GAP43 (growth associated protein 43)
Diseases named in the same sentence as GAP43 in open-access papers (continued):
Sharing a sentence is not in itself a finding about the gene and the disease.
Cerebral ischemia (19 papers, 2014 to 2025). Restriction of arterial blood supply to the brain associated with insufficient oxygenation to support the metabolic requirements of the tissue. "An animal study showed that fasudil has a specific effect on neurovascular injury after cerebral ischemia/reperfusion by inhibiting Rho-A protein expression and increasing the expression of growth-associated protein-43 and claudin-5." (PMID 35659272, 2022). "The recent another study also reported TLR2-deficient mice to show the enhanced repair after focal brain ischemia with higher levels of Gap43 expression and caspases activity for neural plasticity." (PMID 32264906, 2020). "Additionally, it upregulates the expression of growth-associated protein 43 and brain-derived neurotrophic factor following cerebral ischemia-reperfusion, thereby promoting neural regeneration, improving neuronal function, and mitigating cerebral ischemia/reperfusion injury in a rat model." (PMID 39792753, 2025). "Studies have extensively documented significantly increased levels of GAP-43 protein in the peri-infarct region following experimentally induced cerebral ischemia in rodents." (PMID 39215335, 2024). "In another study, authors engineered exosomes containing QCT nanoparticles and monoclonal antibodies against GAP43 (mAb GAP43) and found a therapeutic effect in cerebral ischemia by decreasing reactive oxygen species (ROS)." (PMID 36569877, 2022). "Taken together, these results suggested that Que/mAb GAP43-Exo effectively protected against cerebral ischemia and enhanced the neuroprotective effect of Que by neuron-targeted drug delivery." (PMID 34001136, 2021). "As the neuronal damage contributed to poor outcomes related to recovery after cerebral ischemia/reperfusion injury, Que/mAb GAP43-Exo mediated increase in neuronal survival in the ischemic penumbra was further investigated." (PMID 34001136, 2021). "In our study, a monoclonal antibody against GAP43 (mAb GAP43) was modified on the surface of drug-loaded exosomes to target impaired neurons with a high expression of GAP43 in the ischemic penumbra to improve cerebral ischemia therapy." (PMID 34001136, 2021). "Although less studied in global brain ischemia, focal (cortical) ischemia induces GAP-43 as part of its program to reactivate the growth potential of neurons in the region of axonal sprouting in the peri-infarct cortex." (PMID 25259609, 2014). "Increased expression of GAP-43 in lesion areas after brain ischemia or trauma was related to the activation of endogenous repair mechanism and the promotion of axonal regeneration in the injured nervous system." (PMID 24458787, 2014). "Que/mAb GAP43-Exo may serve a promising dual targeting and therapeutic drug delivery system for alleviating cerebral ischemia/reperfusion injury." (PMID 34001136, 2021). "Besides, increased GAP-43 in the area of infarction in experimental brain ischemia has been reported indicating neuronal injury and possible regeneration." (PMID 34063474, 2021). "Additionally, studies have shown that CSF GAP-43 concentration increase transiently over a period of approximately 5 months during cerebral ischemia and then returns to baseline values, making the interpretation of these findings in VaD even more difficult." (PMID 33203439, 2020). "Brain synaptic regeneration may be related to elevated levels of GAP-43 or Tau proteins, and exercise has been shown to increase expression of GAP-43 in the ischemic area in rats with cerebral ischemia/reperfusion injury." (PMID 32670026, 2020). "The increased expression of GAP-43 may be one of the mechanisms by which functional recovery can be obtained after cerebral ischemia." (PMID 28380213, 2017). "We semi-quantified the SNAP-25, GAP-43 and synaptophysin immunofluorescence since these indicators of synaptic structure have previously been used to evaluate neuroplasticity in other models of cerebral ischemia." (PMID 25259609, 2014).
Cerebral ischemia (continued). "The combination of the BYHWD and physical exercise treatment alleviated the decreases in the SYN, GAP-43 and MAP-2 proteins after the cerebral ischemia." (PMID 28351388, 2017). "However, even observed for nearly one month, no significant improvement of GAP-43 was observed with treatment of 20 mg/kg TMP, which may suggest that GAP-43 was not an effective target for TMP on cerebral ischemia reperfusion injury." (PMID 33531914, 2021).
dementia (17 papers, 2016 to 2025). Loss of intellectual abilities interfering with an individual's social and occupational functions. "In summary, immunohistochemistry and quantitative tests on postmortem brain tissue found reduced GAP-43 in the hippocampus and frontal cortex, which was associated with senile plaques and duration of dementia." (PMID 33578866, 2021). "Also, another study revealed similar results on the significant association between GAP-43 CSF level and AD pathology, including the accumulation of Aβ and neurofibrillary tangles in patients with dementia, particularly in the hippocampus and cortex." (PMID 40831513, 2025). "Additionally, multiple studies have shown that elevated baseline levels of CSF GAP-43 are linked to a more aggressive neurodegenerative process, a quicker rate of cognitive decline, and a higher risk of progressing to dementia." (PMID 39215335, 2024). "Combining GAP-43 with other synaptic biomarkers, such as Ng and SNAP-25, enhances the diagnostic accuracy, allowing for the better differentiation of AD from other dementias." (PMID 40864734, 2025). "First, this study did not observe the correlation of CSF GAP-43 concentration and WM alterations longitudinally to provide more accurate information about the role of GAP-43 in predicting the progression of dementia in patients with cognitive decline." (PMID 40831513, 2025). "Recent studies have suggested that the level of GAP-43 is reduced in the frontal cortex and hippocampus of patients with dementia, reflecting the role of this protein and synaptic integrity in cognitive performance." (PMID 40831513, 2025). "We also applied the GAP-43 gene ID to the Allen Brain Atlas aging and dementia data portal to analyze the GAP-43 mRNA with AD progression." (PMID 37143467, 2023). "The baseline CSF GAP-43 levels differed significantly among the three clinical diagnostic groups (CN controls 5001.05 pg/mL; MCI 5118.80 pg/mL; dementia 6331.05 pg/mL; P < 0.001)." (PMID 36253408, 2022). "We found the group with high GAP-43 (concentration ≥ 4350.7 pg/mL) progressed to dementia more rapidly compared with the group with lower values (concentration < 4350.7 pg/mL) (HR: 2.079, 95% CI: 1.340−3.226, p = 0.001)." (PMID 36611808, 2022). "It was noted that there were significant elevations in CSF GAP-43 in dementia with Lewy bodies and Parkinson’s disease compared to controls." (PMID 33578866, 2021). "The aim was to investigate the relationship between NPS and CSF biomarkers for synaptic (neurogranin [Ng], growth-associated protein 43 [GAP-43]) and axonal (neurofilament light [NFL]) injury in patients with dementia." (PMID 33203439, 2020). "Recently, GAP-43 was proposed for inclusion in the AT(N) framework for AD staging as higher protein levels were found in A + T + N+ subjects, suggesting an early transition to dementia." (PMID 40864734, 2025). "Furthermore, GAP43 and SV2C, synaptic markers of cognitive decline in the brains of dementia patients, were revealed here to interact with CaMKIId and were decreased in the hippocampus of FD mice." (PMID 34758889, 2021). "It is often observed that GAP‐43, SNAP‐25, β‐synuclein, and neurogranin are not changed in non‐AD dementias." (PMID 40522075, 2025).
glioma (17 papers, 2017 to 2025). A benign or malignant brain and spinal cord tumor that arises from glial cells (astrocytes, oligodendrocytes, ependymal cells). "GAP43 has been reported to exert inhibitory effects on the proliferation of glioma cells and breast cancer cells, although the associated inhibitory mechanisms remain not known." (PMID 35884600, 2022). "Knockdown of NNMT reduced the invasive ability of glioma cells, and downregulation of its downstream protein GAP43 occurred due to altered cellular methylation caused by NNMT overexpression." (PMID 35884600, 2022). "During neurogenesis, the neuronal growth associated protein-43 (GAP-43) is highly expressed in axonal growth cones and appears to be required for TM formation between glioma cells." (PMID 32244839, 2020). "To determine whether the Drosophila glial network is susceptible to GAP43 depletion, as it has been described in human tumor cells, we knocked down igloo (igl), the invertebrate GAP43-like gene, in glioma cells." (PMID 31846454, 2019). "Distant intercellular communication in gliomas is based on the expansion of tumor microtubuli, where actin forms cytoskeleton and GAP-43 mediates the axonal conus growth." (PMID 36739296, 2023). "IDH1 wildtype glioma demonstrated significantly more expression of all proteins: GAP-43 (p = 0.009), Cx43 (p = 0.003) and actin (p < 0.001)." (PMID 36739296, 2023). "The top most affected genes included GAP43 which has recently been shown to play a key role in glioma invasiveness through tumor microtube formation and MMP1 which facilitates tumor microtubes' infiltration throughout the brain." (PMID 37689115, 2023). "Upregulated miRNA-363 increased glioma cell viability and proliferation by adjusting the expression level of GAP-43, AKT,cyclin-D1 and other factors." (PMID 34338136, 2021). "Western blotting and immunostaining showed increase in molecular markers (GFAP, NeuF-H, β-tubulin-III, MAP2, Nestin, and GAP43) that confirmed the differentiation of glioma to astrocytes." (PMID 35011307, 2021). "Concerning TNT/TM, it can be concluded that GAP-43 is engaged by glioma cells to form and elongate TMs and to propagate a functional TM network by driving cell migration." (PMID 32244839, 2020). "We showed a difference in the expression of GAP-43 between symptomatic and incidental gliomas." (PMID 36739296, 2023). "Moreover, researchers have found that an inhibitor of miR-363 increases the expression level of GAP43 in glioma cells." (PMID 36777638, 2023). "Thus, the data presented here further support the development of additional local or systemic perioperative therapies, preferentially aimed at GAP-43, the neuron-glioma synapses or other molecular drivers of the malignant tumor cell networks." (PMID 35706996, 2022). "The type 2 tunneling nanotube transcripts (GJA1, GAP43), which overlap with gap junction formations, exhibited a diverse expression in gliomas (GJA1 transcript was significantly overexpressed; however, GAP43 expression was significantly decreased compared to normal brain samples)." (PMID 33096700, 2020). "Thus, GAP43 can help distinguish glioma cells from reactive astrocytes." (PMID 40243478, 2025). "GCL_TI specifically upregulates RG markers TNC, HOPX, PTPRZ1, and VIM, astrocyte markers CLU, LGALS1, as well as genes involved in migration and glioma network formation such as CD44, SPARC, and GAP43 (One peak)." (PMID 36823172, 2023). "The glioma xenograft mouse models were used to verify the regulatory role of NNMT, GAP43, and SIRT1." (PMID 35884600, 2022). "Interestingly, GAP43 can inhibit the activity of protein kinase and AKT signaling pathways in C6 glioma cells, demonstrating a tumor growth inhibitory effect." (PMID 40243478, 2025). "Moreover, the regulatory roles of NNMT, GAP43, and SIRT1 were confirmed in glioma xenograft mouse models." (PMID 35884600, 2022).
glioma (continued). "The knockdown of GAP-43 in mouse brain blocked both TM-non-connected glioma cell invasion and proliferation and intercellular TM connection." (PMID 35847909, 2022). "Consistently, elevated levels of GAP-43 were found in TM-rich human glioma cells and primary stem-like cell lines that had no codeletion of 1p/19q compared to oligodendroglioma cells with a codeletion of 1p/19q." (PMID 32244839, 2020). "Of these 8 genes, 6 (SULT4A1, NDRG4, GAP43, BEX1, HINT1, LZTS1) are believed to act as tumor suppressants, while the remaining two, PKM and VIPR1, have been found to be overexpressed in glioma." (PMID 28957313, 2017).
cognitive decline (16 papers, 2018 to 2026). "Another study demonstrated that baseline CSF GAP-43 was associated with subsequent global cognitive decline and total hippocampal atrophy." (PMID 40993981, 2025). "Recent studies have suggested new biomarkers rather than tau and Aβ such as growth-associated protein 43 (GAP-43) as involved molecules in patients with cognitive decline." (PMID 40831513, 2025). "Several studies have explored the possible association between elevated GAP-43 levels and cognitive decline, including in individuals with MCI." (PMID 39215335, 2024). "We speculated that the APOE ε4 allele played an important role in affecting CSF GAP-43 in the pathogenesis of cognitive decline." (PMID 36611808, 2022). "For example, the downregulation of NEFL, MAP1B, and GAP43—genes essential for axonal stability, cytoskeletal organization, and synaptic plasticity—may underlie the progressive cognitive decline and neurodevelopmental delay frequently reported in POLG‐related encephalopathies." (PMID 41355579, 2026). "Longitudinal studies have indicated that higher CSF GAP-43 levels predict conversion from MCI to AD, and are associated with accelerated cognitive decline." (PMID 40864734, 2025). "Phosphorylation of GAP-43 is known to play a role in axon growth and synaptic plasticity, and we also observe this GAP-43 proteoform is associated with reduced cognitive decline." (PMID 40334744, 2025). "Genetic factors also influence GAP-43 expression, with APOE ε4 carriers exhibiting higher CSF GAP-43 levels and a more rapid increase over time, indicating greater early synaptic vulnerability and cognitive decline acceleration." (PMID 40864734, 2025). "Evaluating the potential association between GAP-43 and imaging findings in patients with cognitive decline can provide more evidence on the role of GAP-43 in the early diagnosis of these patients." (PMID 40831513, 2025). "Since cognitive decline in AD continuum is partly attributed to synaptic dysfunction, GAP-43 is under scrutiny as a marker for both synaptic dysfunction and neurodegeneration." (PMID 39215335, 2024). "Our study observed a significant association between CSF GAP-43 concentration and WM microstructural findings in different brain tracts of patients with various ATN groups, suggesting GAP-43 as a reliable and accurate biomarker in the early detection of patients with cognitive decline." (PMID 40831513, 2025). "We suspected that the effects of CSF GAP-43 in the pathophysiology of cognitive decline may be relevant to APOE ε4 status." (PMID 36611808, 2022). "Third, we concentrated on baseline CSF GAP-43 level to predict cognitive decline and brain atrophy." (PMID 36611808, 2022). "The high cholesterol diet did not exacerbate age-dependent cognitive decline and hippocampal neuronal death, and even greatly mitigated decreases of synaptophysin and growth associated protein 43 expression in the hippocampus of aged mice." (PMID 29896426, 2018). "Moreover, most recent studies have shown increased CSF levels of GAP-43 in different brain areas of patients with AD continuum, suggesting this protein as a reliable biomarker in the diagnosis and monitoring of patients with cognitive decline." (PMID 40831513, 2025). "Hence, we supposed that CSF GAP-43 could be an early biomarker for cognitive decline and the effects of CSF GAP-43 on cognition may be correlated with APOE ε4 status and the number of ε4 alleles." (PMID 36611808, 2022). "Furthermore, higher CSF levels of GAP-43 have been associated with worse cognitive performance and faster symptom worsening in AD, indicating that GAP-43 may be a proxy of synaptic dysfunction that parallels cognitive decline in the disease." (PMID 38172114, 2024).
schizophrenia (15 papers, 2011 to 2025). A major psychotic disorder characterized by abnormalities in the perception or expression of reality. "SNAP23, SNAP25, SNCA, and GAP43, present in the presynaptic membrane, play essential roles in neurotransmitter release and plasticity and are associated with schizophrenia." (PMID 35062349, 2022). "Mutations in the gene encoding Ng as well as alterations of GAP-43 levels in the hippocampus have also been associated with schizophrenia." (PMID 33203439, 2020). "Regarding these genes and their potential role in schizophrenia and related neuropsychiatric conditions, non-synonymous point mutations in GAP43 were recently identified in two unrelated schizophrenia cases in a next-generation sequencing study." (PMID 24650298, 2014). "Moreover, in patients with schizophrenia, a reduction in gene expression related to cytoskeletal modification, such as growth-associated protein 43 (GAP43) and neuronal navigators (NAV1), was reported." (PMID 36833173, 2023). "Additionally, Ingenuity Global Functional Analysis revealed significant enrichment of the identified protein dataset for proteins previously shown to be linked to schizophrenia, including GAP43, VDAC1 and SNCB, all of which have been shown to play a role in synaptic communication." (PMID 28570644, 2017). "This study shows that the schizophrenia risk gene NRG1 controls the development of callosal connections and implicates NRG1 signaling in the regulation of GAP43, a key protein for axonal growth." (PMID 38918041, 2024). "Similar to tau, GAP-43 is crucial for outgrowth of neuronal extensions, and not surprisingly, abnormalities in the expression of GAP-43 have been associated with both schizophrenia and autism." (PMID 34827371, 2021). "At the molecular level, numerous mRNA transcripts and proteins are altered in both schizophrenia and bipolar disorder, including brain-derived neurotrophic factor (BDNF), glutamic acid decarboxylase-67 (GAD-67) and growth-associated protein-43 (GAP-43)." (PMID 22427805, 2012). "It has already been shown that mutations in ELAVL4 are associated with an earlier onset of Parkinson’s disease, and the dysregulated expression of its known target, GAP43, has been observed in the frontal cortices and hippocampi of individuals with schizophrenia." (PMID 40362522, 2025). "Interestingly, existing data on the expression level of GAP43 in schizophrenia patients has been controversial." (PMID 37815900, 2024). "Indeed, overexpression of GAP-43 is suggestive for dysfunction in synaptic connections in autism and schizophrenia." (PMID 35943710, 2022). "It has been suggested that vitamin D deficiency in the developmental brain could be part of the pathophysiology of schizophrenia through the deregulation of drebrin and GAP-43." (PMID 31284484, 2019). "Moreover, decreased GAP-43 expression in the inner molecular layer and stratum radiatum of the CA2 has been found in the hippocampi of dead patients with schizophrenia and BD, suggesting that loss of neuroplasticity may be a cause of these psychiatric disorders." (PMID 40362522, 2025). "Noteworthy, the altered expression of GAP43, one of known targets of ELAVL4, is reported in the frontal cortices and the hippocampus of patients with schizophrenia." (PMID 21674006, 2011).